RNU6-834P (RNA, U6 small nuclear 834, pseudogene)
Gene: Small nuclear RNA gene on chromosome 12 (49,593,104 to 49,593,213, forward strand). Ensembl gene ENSG00000199237.
Homologues: Orthologues: chimpanzee U6 (97% identical), macaque U6 (93% identical), mouse Gm25814 (78% identical), rabbit U6 (78% identical), guinea pig U6 (77% identical), pig U6 (73% identical), dog U6 (71% identical). Paralogues in human: RNU6-1094P (85% identical), RNU6-727P (85% identical), RNU6-1309P (85% identical), RNU6-1091P (84% identical), RNU6-1209P (84% identical), RNU6-1287P (84% identical), RNU6-19P (84% identical), RNU6-24P (84% identical), RNU6-949P (84% identical), RNU6-1011P (83% identical), RNU6-1020P (83% identical), RNU6-1024P (83% identical), and 1285 more.